IRS1 (insulin receptor substrate 1)
Diseases named in the same sentence as IRS1 in open-access papers (continued):
Sharing a sentence is not in itself a finding about the gene and the disease.
autistic disorder (1 paper, 2016). "Our study is the first pilot to report an association of the IRS1 with autistic disorder/ASD." (PMID 27483248, 2016). "Interestingly, when we analyzed the differences between patients with autistic disorder and healthy individuals, rs1801123 of IRS1 showed a statistically more significant association." (PMID 27483248, 2016). "In the present study, we found that rs1801123 of IRS1 was associated with ASD, and the association was shown more strongly in patients with autistic disorder." (PMID 27483248, 2016). "Replication studies are needed to determine the association between the IRS1 and autistic disorder/ASD, as well as the lack of association of IRS2, analyzing more polymorphisms in addition to rs1801123 and rs4773092." (PMID 27483248, 2016). "Thus, relatively low activities of IGF pathway molecules such as IGF1, IRS1 and IRS2 may play a role as risk factors in the pathophysiology of autistic disorder/ASD, leading to the growth and development retardation." (PMID 27483248, 2016).
benign prostate hyperplasia (1 paper, 2012). "Our results imply that IRS-1 plays a poorly defined but important role in the pathogenesis of human diseases that exhibit abnormal proliferation of cells, such as cancers, benign prostate hyperplasia, and atherosclerotic coronary artery disease." (PMID 22788551, 2012).
brain infarcts (1 paper, 2021). "First, with the observed association of pT308AKT1 and IRS1 with brain infarcts, one plausible mechanism would be through more vessel pathology, yet our data do not support such a pathophysiologic pathway." (PMID 33858515, 2021).
brain injury (1 paper, 2021). Acute and chronic (see also brain INJURIES, CHRONIC) injuries to the brain, including the cerebral hemispheres, CEREBELLUM, and brain STEM. "Together, our findings suggested that neuronal and endothelial IRS-1 had opposite effects on the neurovascular integrity and damage after neonatal HI brain injury and that endothelial IRS-1 worsens neurovascular integrity after HI via mTOR-mediated tight junction protein disassembly." (PMID 34226528, 2021).
brain tumor (1 paper, 2021). "The enhancement of BBB permeability by endothelial IRS-1 overexpression, however, suggests endothelial IRS-1 as a good candidate for augmenting therapeutic drug delivery across the BBB for the treatment of brain disorders, such as brain tumor or neurodegenerative diseases." (PMID 34226528, 2021).
breast adenocarcinoma (1 paper, 2008). "Transgenic mice for the IGF-I pathway, over-expressing IGF-I, IGF-IR, or IRS1 and IRS2 in the mammary gland, all develop breast adenocarcinomas." (PMID 18611244, 2008).
breast invasive ductal carcinoma (1 paper, 2023). "IRS1 expression is elevated in breast invasive ductal carcinoma and associated with p-Akt expression and a poor prognosis for the patients." (PMID 36768755, 2023).
chronic hepatitis C (1 paper, 2012). "TNF-α is upregulated in patients with chronic hepatitis C (CHC) and this cytokine has been shown to interrupt insulin signaling via reduced-tyrosine phosphorylation of IRS-1 and decreased ability of IRS-1 to associate with the insulin receptor." (PMID 23049551, 2012).
colitis (1 paper, 2023). Inflammation of the colon. "Moreover, IRS1-overexpressing Treg cells were unable to suppress the pathogenic effects of conventional T cells in a transfer-induced colitis model." (PMID 36768873, 2023). "To examine the role of IRS1 in Treg cells in vivo, we performed transfer-induced colitis experiments." (PMID 36768873, 2023).
colorectal adenoma (1 paper, 2014). An adenoma that arises from the colon or rectum. "Using real-time PCR, we found that the expression of downstream transcriptional targets of the β-catenin/TCF signaling pathway that are known to be elevated in colorectal adenoma and carcinomas, such as AXIN2, NKD1, and IRS1, were not decreased by RAP treatment in the HCECs." (PMID 24763434, 2014).
COVID-19 (1 paper, 2022). A disease caused by infection with severe acute respiratory syndrome coronavirus 2. "In summary, the expression patterns of CD36, GLUT2, IRS1, IRS2, PDX1, and PPARG in the pancreas were altered upon SARS-CoV-2 infection, implying that islet function may be compromised in patients with COVID-19." (PMID 35343389, 2022).
diabetic cardiomyopathy (1 paper, 2017). Diabetic cardiomyopathy is a disorder of the heart muscle in people with diabetes. "A previous study reported that sustained activation of Foxo1 or Foxo3 leads to diminished insulin responsiveness and impaired glucose metabolism in cardiac myocytes, and Foxo1 activation triggers diabetic cardiomyopathy through downregulation of Irs1 in mice." (PMID 28887535, 2017).
ductal carcinoma in situ (1 paper, 2021). "In normal human breast tissues and ductal carcinoma in situ, expression patterns of IRS-1 correlate with those of STAT6 and p-STAT6." (PMID 34769439, 2021).
endometrial adenocarcinoma (1 paper, 2021). "In our results, IGF1 and IRS1, essential factors in the glucose metabolism, thermogenesis, and glucose catabolic process 30, were considered as the potential target genes of FTO in the regulation of endometrial adenocarcinoma." (PMID 34149936, 2021).
epithelial ovarian tumors (1 paper, 2024). "IRS1 is frequently upregulated in malignant epithelial ovarian tumors, and its overexpression in the mouse mammary gland leads to tumorigenesis through tyrosine phosphorylation, activating AKT and ERK1/2." (PMID 38272982, 2024).
familial dilated cardiomyopathies (1 paper, 2013). "Here we show that nexilin, a F-actin binding protein implicated in the pathogenesis of familial dilated cardiomyopathies, preferentially binds to IRS1 over IRS2 to influence glucose transport in skeletal muscle cells." (PMID 23383252, 2013).
glomerulosclerosis (1 paper, 2024). A hardening of the kidney glomerulus caused by scarring of the blood vessels. "IRS1/PI3K/AKT pathway was the main signal regulation pathway of podocyte IR, and blocking this pathway would induce EMT and glomerulosclerosis in DN podocytes." (PMID 38617433, 2024). "IRS1/PI3K/AKT signaling pathway was involved in glomerular podocyte EMT and glomerulosclerosis." (PMID 38617433, 2024).
hCMV infection (1 paper, 2022). "Finally, IRS1 and TRS1, which inhibit the establishment of an antiviral state in infected cells, in particular by antagonizing the autophagy pathway induced upon hCMV infection, were also detected." (PMID 36146834, 2022).
hypercortisolemia (1 paper, 2022). "At the metabolic level, the observed increased availability of IRS2, IGFBP2 and, to a lower extent, IRS1 after treatment suggested an elevated sensitivity to insulin in VAT under hypercortisolemia." (PMID 35737302, 2022).
injury (1 paper, 2021). Damage inflicted on the body as the direct or indirect result of an external force, with or without disruption of structural continuity. "In this study, we used transgenic rat pups in which IRS-1 was respectively overexpressed in the neuronal or the endothelial cells to investigate the respective effect and the underlying mechanism of IRS-1-regulated neurovascular integrity after neonatal HI brain injury." (PMID 34226528, 2021). "However, little is known on whether IRS-1 plays a similar role in neuronal cells and vascular endothelial cells of the neurovascular unit in neuroprotection against neonatal HI brain injury." (PMID 34226528, 2021).
intestinal tumors (1 paper, 2009). "Once again, however, it is likely that IRS-1 function is cell context-dependent because deletion of Irs-1 in Apcmin-/+(Min)/β-catenin-derived intestinal tumors decreases tumor incidence and growth and increases irradiation-induced apoptosis in the intestinal crypt." (PMID 19534786, 2009).
invasive carcinoma (1 paper, 2019). A carcinoma that is not confined to the epithelium, and has spread to the surrounding stroma. "For example, IRS-1 is expressed at high levels in normal breast epithelium and benign breast lesions but expression decreases during the progression to poorly differentiated, invasive carcinomas." (PMID 31393907, 2019).
lentivirus infection (1 paper, 2023). Virus diseases caused by the Lentivirus genus. "To further investigate the role of the IRS1-PTEN axis in GC cells, we constructed IRS1 stable-knockdown cell lines of BGC803 and MKN45 using two IRS1-specific short hairpin RNAs (shRNAs) by lentivirus infection." (PMID 36774408, 2023).
lymphoma (1 paper, 2015). A malignant (clonal) proliferation of B- lymphocytes or T- lymphocytes which involves the lymph nodes, bone marrow and/or extranodal sites. "Although further analysis is required to support this idea, we cannot completely rule out that Ik-1 and MZF1 act as tumor suppressors in this lymphoma through targeting the expression of IGF-IR and IRS-1." (PMID 25884514, 2015).
malaria (1 paper, 2022). Malaria is a serious and sometimes fatal disease caused by a parasite that commonly infects a certain type of mosquito which feeds on humans. "Six genes (TGFB1, CD36, THBS1, FABP1, PCK1, and IRS1) were involved with malaria, PPAR signaling, and the adipocytokine signaling pathway." (PMID 36193307, 2022). "Among them, malaria, PPAR signaling, and the adipocytokine signaling pathway reached statistical significance (FDR value of <1 and p < 0.05) and included TGFB1, CD36, THBS1, FABP1, PCK1, and IRS1." (PMID 36193307, 2022).
meningioma (1 paper, 2017). A generally slow growing tumor attached to the dura mater. "In human meningioma cells, we observed an increase in Akt phosphorylation levels and a decrease in IRS1 phosphorylation levels with everolimus, underlining the potential utility of combination therapeutic strategies to block this positive feedback on the Akt oncogenic pathway." (PMID 28903425, 2017).
metastatic cancers (1 paper, 2014). A carcinoma which has spread from the original site of growth to another anatomic site. "Most metastatic cancers express higher levels of IRS-2 as compared to IRS-1." (PMID 24885964, 2014).
metastatic prostate carcinoma (1 paper, 2013). A carcinoma that arises from the prostate gland and has spread to other anatomic sites. "In addtion, the identified interactions in metastatic prostate cancer contain several experimentally confirmed targets of hsa-miR-143 and −145, including CLINT1, CDKN1A, IRS1, MAPK7, PPM1D and SOD2." (PMID 23782521, 2013).
metastatic tumors (1 paper, 2012). "Primary and metastatic tumors, when compared to colonic epithelium, contained higher numbers of cells expressing IRS1 (80.8±6.2% for primary and 81.3±6.6% for metastatic CRC versus 59.1±5.6% for colonic epithelium, P = 0.013 and P = 0.014, respectively)." (PMID 22558377, 2012).
Miscarriage (1 paper, 2024). A pregnancy that ends at a stage in which the fetus is incapable of surviving on its own, defined as the spontaneous loss of a fetus before the 22th week of pregnancy. "The current study demonstrates the reduction in the insulin receptor gene IRS1 expression among females who experienced miscarriages." (PMID 39205919, 2024).
mood disorder (1 paper, 2021). A cognitive disorder a disturbance in which the person's mood is hypothesized to be the main underlying feature. "Brain IR/IRS-1 signaling is important for energy homeostasis, cellular metabolism, and mood disorders, while most of these effects are thought to occur in neurons." (PMID 34149862, 2021).
morbid obesity (1 paper, 2020). An excess of body weight, normally defined as an individual with a body mass index greater than 35 or a body weight greater than one hundred percent of ideal body weight. "First, we wanted to know whether the levels of a particular fatty acid could be associated with the gene expression of IRS1, p85α or p110β, taking into account all patients (non-obese patients and those with morbid obesity)." (PMID 32806641, 2020). "Material and Methods: We analyzed IRS1, p85α, and p110β mRNA expression and the fatty acid composition of phospholipids in visceral adipose tissue from patients with morbid obesity and from non-obese patients." (PMID 32806641, 2020). "As in previous studies, we found decreased levels of IRS1 VAT from patients with morbid obesity, independent of the insulin-resistant state, with metformin slightly increasing IRS1 expression." (PMID 32806641, 2020).
muscle atrophy (1 paper, 2013). "In turn, the loss of IRS-1 caused the forkhead transcription factor-3- (FOXO3-) dependent induction of muscle atrophy F-box protein (MAFbx)/atrogin-1, a dominant mediator of proteolysis in atrophic muscle." (PMID 23762056, 2013). "Since amino acid sequence similar to Cblin in soy glycinin inhibited denervation-mediated ubiquitination of IRS-1, this sequence of soy is a potent functional peptide against muscle atrophy." (PMID 23762056, 2013).
nonalcoholic steatohepatitis (1 paper, 2023). "For example, the epigallocatechin-3-gallate supplement has been shown to improve insulin sensitivity and promote the functional recovery of insulin receptor substrate-1 in a model of nonalcoholic steatohepatitis." (PMID 37242133, 2023).
oral carcinoma (1 paper, 2022). "For example, in the context of oral carcinoma, miR-370 controls the expression of insulin receptor substrate-1 and suppresses tumor growth." (PMID 35356749, 2022).
ovarian serous cystadenocarcinoma (1 paper, 2021). A malignant serous cystic epithelial neoplasm arising from the ovary. "More interestingly, the highest association scores between miR-150-5p/3p and IRS1 or IGF1R were found in 481 ovarian serous cystadenocarcinoma tissues through pan-cancer analysis by CancerMiner." (PMID 33723215, 2021).
overactive bladder (1 paper, 2024). Symptom of overactive detrusor muscle of the urinary bladder that contracts with abnormally high frequency and urgency. "Mice with conditional hepatic double-knockout of Irs1 and Irs2 show characteristics of T2DM and overactive bladder." (PMID 39292699, 2024).
pancreatic ductal adenocarcinoma (1 paper, 2021). An infiltrating adenocarcinoma that arises from the epithelial cells of the pancreas. "Previous literature revealed that the upregulation of TGFB2 expression can mediate epithelial-mesenchymal transition of pancreatic ductal adenocarcinoma, and MET, IRS1, and BCL2L1 are also demonstrated to be related to PAAD initiation, progression, and metastasis." (PMID 34777634, 2021).
peripheral nerve injury (1 paper, 2025). Injury to a peripheral nerve. "Thus, after peripheral nerve injury, increased TNF‐α/FFAs activate JNK‐1 and mTOR pathways, directly promoting IRS‐1 phosphorylation at inhibitory serine sites (Ser307/Ser612/Ser616)." (PMID 41414737, 2025).
placental insufficiency (1 paper, 2015). Failure of the placenta to deliver an adequate supply of nutrients and oxygen to the fetus. "In rodent models of placental insufficiency, young adolescent male offspring show altered GLUT4 transport in conjunction with an increased phosphorylation of IRS-1, which is known to blunt the physiological response to insulin by reducing the coupling efficiency of the insulin receptor and IRS-1." (PMID 25685986, 2015). "IRS-1 is also known to complex with PI3-kinase, and in young male low birth weight offspring, reduced expression of the p85 regulatory subunit and p110β catalytic subunit of PI3K has also been observed in rodent, as well as larger animal (e.g., sheep) models of placental insufficiency." (PMID 25685986, 2015).
primary hypertension (1 paper, 2020). "In the experimental model of primary hypertension we observed a decrease in myocardial phosphorylation of IRS-1 (Ser302) (−28.9%, P < 0.05) and AKT/PKB (Ser473) proteins (–16.9%, P < 0.05) with simultaneous increase in the total CS expression (+23.8%, P < 0.05) compared to the normotensive rats." (PMID 32326330, 2020).
rectal cancer (1 paper, 2024). A primary or metastatic malignant neoplasm that affects the rectum. "Tumor IRS1 expression was related to the survival of rectal cancer patients." (PMID 38406803, 2024).
renal failure (1 paper, 2020). "Therefore, the activation of the PI3K/Akt/IRS-1 and I-κB/NF-κB pathways induces a decrease in the activities of enzymes, such as phosphatase and protein serine/threonine kinase, which are crucial in the pathogenesis of renal failure." (PMID 32190104, 2020).
renal fibrosis (1 paper, 2025). A final common manifestation of a wide variety of chronic kidney diseases characterized by glomerulosclerosis and tubulointerstitial fibrosis. "In a streptozotocin (STZ)‐induced DKD rat model, Ast‐Por‐Rhe supplementation, as a functional food intervention, significantly mitigated renal metabolic dysfunction, evidenced by enhanced IRS1/PI3K/Akt activity, reduced lipid peroxidation, and improved renal fibrosis." (PMID 41323824, 2025).
Splenomegaly (1 paper, 2023). Abnormal increased size of the spleen. "Mice receiving naïve CD4 T cells + IRS1-overexpressing Treg cells also had shorter colons, developed splenomegaly, and had thicker epithelial layers." (PMID 36768873, 2023).
teratoma (1 paper, 2022). A non-seminomatous germ cell tumor characterized by the presence of various tissues which correspond to the different germinal layers (endoderm, mesoderm, and ectoderm). "In our study, CARD11(caspase recruitment domain family member 11) (mutated in 18% intracranial teratomas), IRS1(insulin receptor substrate 1) (18%), PSMD11(16%), RELN(16%), RRAS2(16%), SMC1A(16%), SYNE1(16%) and ZFHX3(16%) were the tumor-related genes with the highest mutation rates in our cohort." (PMID 36457486, 2022).
Tremor (1 paper, 2020). An unintentional, oscillating to-and-fro muscle movement about a joint axis. "The overlap between PD patients and control in the level of p-IRS-1S312 in blood NDEVs may limit the application of p-IRS-1 as a diagnostic biomarker for PD, but the association with tremor may provide another role as the segregating biomarker for PD." (PMID 33344443, 2020). "In addition, several serine phosphorylation sites are available on IRS-1, and the present study demonstrated that while p-IRS-1S312 was associated with PD, and the severity of tremor in PD patients." (PMID 33344443, 2020).
Uterine leiomyoma (1 paper, 2013). The presence of a leiomyoma of the uterus. "Gene expression of IRS1 was found to be increased in uterine leiomyomas in this study." (PMID 23818951, 2013).
β-cell deficiency (1 paper, 2022). "This research indicates that GQD and metformin significantly increased the α-cell proliferation of β-cell deficiency induced diabetic rats by restoring Cdk4 and Irs1 gene expression." (PMID 35858880, 2022).